POU3F3 (POU class 3 homeobox 3)
Diseases named in the same sentence as POU3F3 in open-access papers (continued):
Sharing a sentence is not in itself a finding about the gene and the disease.
tumor (continued). "Among the three lncRNAs, POU3F3 provided the highest diagnostic power for detection of ESCC (AUC = 0.842; sensitivity, 72.8%; and specificity, 89.4%), suggesting that plasma POU3F3 could serve as a promising tumor marker for ESCC detection." (PMID 25608466, 2015). "In summary, our results suggested that increased plasma lncRNA POU3F3 can be used as ideal tumor biomarker for ESCC detection, and that combination of POU3F3 and SCCA has a higher positive diagnostic rate of ESCC than POU3F3 or SCCA alone, in particular at its early stage." (PMID 25608466, 2015). "Plasma POU3F3 was confirmed as a potential biomarker for diagnosis of ESCC, and the combination of POU3F3 and SCCA was efficient for early tumor screening." (PMID 32851080, 2020). "This factor and especially the long non coding (lnc) RNA linc-POU3F3, which was also among the upregulated DEG, are known to play a role in tumor cell proliferation, inhibition of apoptosis, as well as in angiogenesis in several malignancies." (PMID 33046735, 2020). "Several exosomal lncRNAs, such as MALAT-1, linc-POU3F3, ZFAS1, promote tumor growth and migration, prevent tumor cell apoptosis, or induce angiogenesis." (PMID 29456536, 2018). "Linc-POU3F3 is increased in ESCC samples, which, through interactions with EZH2 to promote methylation of POU3F3, then promote tumor development." (PMID 26974151, 2016). "Among them, HOTAIR, AFAP1-AS1, POU3F3, HNF1A-AS1, PlncRNA1, SPRY4-IT1, ENST00000435885.1 and ENST00000547963.1 were significantly higher in most of ESCC tumor tissues compared with paired adjacent normal tissues." (PMID 25608466, 2015). "Expression levels of POU3F3 and MEG3 were inversely correlated across tumor tissues." (PMID 35201451, 2021). "POU3F3 and miR-30d-5p were significantly and inversely correlated across tumor tissues (r = − 0.87, p < 0.0001), but not in adjacent healthy tissues (r = − 0.15, p = 0.18)." (PMID 32615948, 2020). "Furthermore, we also found that exosomal lncRNA POU3F3 levels were decreased 4 weeks after CCRT, and they were upregulated again in patients with tumor progression (p < 0.001)." (PMID 32637576, 2020). "Plasma POU3F3 could serve as a potential biomarker for diagnosis of ESCC, and the combination of POU3F3 and SCCA was more efficient for ESCC detection, in particular for early tumor screening." (PMID 25608466, 2015). "Additionally, the expression of POU3F3 and MEG3 correlate in tumour tissue but not in normal tissue, pointing towards some undiscovered pathological mediators between POU3F3 and MEG3." (PMID 41463281, 2025). "Plasma levels of lncRNA POU3F3 were not affected by tumor size." (PMID 30602452, 2019). "In addition, plasma levels of lncRNA POU3F3 were affected by tumor metastasis but not by metastasis." (PMID 30602452, 2019). "However, linc-POU3F3 expression did not correlate with patients' gender, age, tumor size, T grade or M grade." (PMID 26510906, 2016). "LncRNA POU3F3 may participate in tumor metastasis but not growth by interacting with TGF-β1." (PMID 30602452, 2019). "It was observed that POU3F3 and MEG3 were significantly and inversely correlated across tumor tissues but not normal tissues." (PMID 35201451, 2021). "We demonstrated that linc-POU3F3 was overexpressed in CRC tissues compared with the adjacent non-tumor tissues and positively correlated with the tumor histology grade and N grade." (PMID 26510906, 2016).
cancer (23 papers, 2016 to 2026). A tumor composed of atypical neoplastic, often pleomorphic cells that invade other tissues. "POU3F3 from cancer cells can be transferred to normal fibroblasts in the exosomes, subsequently transform and activate fibroblasts into cancer-associated fibroblasts." (PMID 40781643, 2025). "Other IGs discussed in this study and linked with cancer and neurodevelopmental disorders were Pou3f3, bHLHE22, ASCL5, and Hist2h2be." (PMID 34306008, 2021). "TGF-β1 inhibitor partially rescued the inhibited cancer cell migration and invasion caused by lncRNA POU3F3 overexpression." (PMID 30602452, 2019). "POU3F3 adjacent noncoding transcript 1 (PANTR1) is an oncogenic long noncoding RNA that is located at 4 kb upstream of the protein-encoding POU3F3 gene that has a substantial influence on a variety of cellular features in various types of cancer." (PMID 36861062, 2023). "POU3F3 promotes the transformation of normal fibroblasts into CAFs, which are known to secrete cytokines that support cancer cell survival and chemoresistance." (PMID 40781643, 2025). "Fibroblasts activated by exosomal lnc-POU3F3, in turn, promote the proliferation and cisplatin resistance of cancer cells through the paracrine secretion of an inflammatory cytokine, IL-6." (PMID 33050576, 2020). "The lnc-POU3F3 lncRNA is transferred from cancer cells to fibroblasts via exosomes and activated fibroblasts." (PMID 33050576, 2020). "qRT-PCR analysis further confirmed that the lncRNA POU3F3 level in exosomes was almost equal to that in CM/cancer, suggesting that exosomes were the main carrier for extracellular lncRNA POU3F3." (PMID 32637576, 2020). "POU3F3 was upregulated, while miR-30d-5p was downregulated in cancer tissues than in adjacent healthy tissues of NSCLC patients." (PMID 32615948, 2020). "Prior studies have shown that lncRNA POU3F3 is expressed aberrantly and has oncogenic roles in several cancers." (PMID 32637576, 2020). "Circulating lncRNAs as biomarker for cancer diagnosis have been the subject of extensive research for years, such as POU3F3, HOTAIR, H19, MALAT-1, and so on." (PMID 27888803, 2016). "Notably, lncRNA POU3F3 was reported to promote ESCC cell proliferation and cisplatin resistance through exosomal POU3F3-induced transformation of normal fibroblasts to cancer-associated fibroblasts in ESCC." (PMID 35645836, 2022). "Furthermore, in NSCLC cell lines, the overexpression of POU3F3 led to the negative regulation of miR-30d-5p to facilitate the proliferation of cancer cells." (PMID 35155437, 2022). "In addition, the rescue experiment showed that MEG3 overexpression attenuated the enhancing effects of POU3F3 overexpression on cancer cell proliferation (p < 0.05)." (PMID 35201451, 2021). "POU3F3 has been characterized as an oncogenic lncRNA in many types of cancers." (PMID 35201451, 2021). "The expression levels of lncRNA POU3F3 in CM from ESCC cells (CM/cancer) were largely unchanged upon RNase A digestion but significantly declined when treated with RNase A and Triton X-100 simultaneously, suggesting that it was mainly encased within the membrane instead of directly secreted." (PMID 32637576, 2020). "In light of these findings, we then determined whether cancer-secreted lncRNA POU3F3 could serve as a predictive marker for response to cisplatin-based CCRT in ESCC." (PMID 32637576, 2020). "In addition, overexpression of miR-30d-5p played an opposite role and attenuated the effects of overexpressing POU3F3 on cancer cell proliferation, migration and invasion." (PMID 32615948, 2020). "We also found that lncRNA POU3F3 could be transferred from cancer cells to NFs via exosomes and mediate NF activation." (PMID 32637576, 2020). "In addition to the BMP pathway and cancer metastasis, we revealed a novel regulatory function of linc-POU3F3 in autophagy within CRC cells." (PMID 26510906, 2016).
cancer (continued). "Additionally, previous studies noted that the POU3F3 mRNA level was decreased in various cancers; therefore, we plotted the POU3F3 mRNA levels against linc-POU3F3 expression." (PMID 26510906, 2016). "In addition, in the upstream mechanism, POU3F3 overexpression activated the invasion and migration of cancer cells via miR-30d-5p, which was obviously 2021associated with the depth of tumor invasion and the degree of lymph node metastasis in esophageal carcinoma." (PMID 35155437, 2022). "Therefore, POU3F3 could also interact with other downstream pathways to reverse the enhancing effects of MEG3 inhibition on cancer cell migration and invasion." (PMID 35201451, 2021). "CASC9, POU3F3, SNHG3, CDKN2B-AS1, and ZEB2-AS1 are predicted to sponge several miRNAs (in cancer cells) to promote cancer proliferation." (PMID 37190145, 2023). "Differential analysis on cancer reads of the KIRC against the other 8 PDX types revealed 1,181 DE genes (q< 0.05, BH adjusted), with the lowest q-value identified for POU3F3, SLC28A1, and CDH6 genes." (PMID 35079698, 2021). "Our in vitro cell experiments suggest that lncRNA POU3F3 is likely an upstream activator of TGF-β1 in the regulation of migration and invasion of cancer cells." (PMID 30602452, 2019). "Linc-POU3F3 is increased in ESCC tissues and contributes to development of cancer through interactions with EZH2 to promote methylation of POU3F3." (PMID 28404901, 2017). "We knocked down linc-POU3F3 expression in LOVO and SW480 cancer cells by transfection with siRNAs, si-linc-POU3F3." (PMID 26510906, 2016). "Furthermore, linc-H19 was suggested to be tightly linked to tumorigenesis and to be prognostic significant for cancer progression in CRC; therefore, we compared the prognostic data of linc-H19 with that of linc-POU3F3 within these 45 cases CRC patients to assess the prognostic value of linc-POU3F3." (PMID 26510906, 2016). "Compared with control (C) and negative control (NC), lncRNA POU3F3 overexpression and TGF-β1 (10 ng/ml) treatment led to significantly promoted cancer cell migration and invasion (P<0.05)." (PMID 30602452, 2019).
neurodevelopmental disorder (2 papers, 2021 to 2022). A behavioral and cognitive disorder with onset during the developmental period that involves impaired or aberrant development of intellectual, motor, or social functions. "For example, POU3F3 is a well-known TF involved in the development of the central nervous system and is related to many neurodevelopmental disorders." (PMID 36525361, 2022).
POU3F3 also shares sentences with these, for which no sentence is quoted: breast carcinoma (3 papers); hepatocellular carcinoma (2); adenocarcinoma (1); central nervous system tuberculosis (1); endometrial carcinoma (1); glioblastoma (1); metastatic melanoma (1); renal hypoplasia (1); speech delays (1); squamous cell carcinoma (1); triple-negative breast carcinoma (1).